IL6 (interleukin 6)
Diseases named in the same sentence as IL6 in open-access papers (continued):
Sharing a sentence is not in itself a finding about the gene and the disease.
gastric cancer (continued). "The gp130F/F mutation impairs SOCS3-mediated negative feedback of STAT3 signaling, leading to hyperactivation of the IL-6/STAT3 pathway that is frequently dysregulated in human gastric cancer." (PMID 40673273, 2025). "The anti-tumor drug 3,3’-diindolylmethane (DIM) activates NF-κB signaling in gastric cancer-TA-MSCs, enhancing their secretion of IL-6, IL-8 and CCL2, which in turn promotes cancer cell proliferation." (PMID 40676710, 2025). "In summary, our work uncovers a novel oncogenic axis in EBV-associated gastric cancer, whereby EBV-encoded miR-BART20-3p directly targets PPARα to unleash IL-6–driven inflammatory signaling, thereby promoting tumor cell proliferation and migration." (PMID 40732023, 2025). "Studies have shown that gastric cancer-derived MSCs activate neutrophils via the IL-6/STAT3 axis, promoting the migration of gastric cancer cells and the formation of endothelial cell tubes in vitro." (PMID 40387965, 2025). "Recent studies have indicated that IL-6 is upregulated in gastric cancer tissues, serving as a marker for poor prognosis." (PMID 40051564, 2025). "Comparison of tumor markers and IL6 levels in 2 groups of patients with advanced gastric cancer before and after treatment." (PMID 40958249, 2025). "TNF‐α is a key marker for assessing the prognosis of gastric cancer patients, while IL‐6 enhances AGS cell invasiveness, contributing to metastatic progression." (PMID 40838679, 2025). "SARIFA-positive cases have also been associated with lower expression of IL6 and TNFA in gastric cancer." (PMID 40055484, 2025). "In the comparison of metabolite interference group and M1 group marker proteins in gastric cancer cells, there were significant differences in IL-6, CXCL9, CXCL10 and CXCL11." (PMID 39991579, 2025). "Tumor-associated mesenchymal stem cells promote immunosuppression in gastric cancer, often through the modulation of cytokines such as IL-6 and IL-10." (PMID 40723172, 2025). "MALAT1 in gastric cancer also inhibits autophagy flux and stimulates IL-6 by regulating the PTEN/AKT/mTOR pathway, thereby transforming fibroblasts into myofibroblasts." (PMID 40297152, 2025). "A 55‐year‐old woman complained of recurrent gastric carcinoma, which was associated with chronic gastritis and high systemic inflammatory markers (elevated CRP and IL‐6)." (PMID 41179371, 2025). "Levels of interleukin 6 (IL-6) are also elevated in H. pylori-positive individuals with gastric carcinoma." (PMID 40004976, 2025). "Tα1 increased the percentage of CD4+CD25+Foxp3+ (suppressive antitumor-specific Tregs), Tregs, IL-1β, TNF-α, and IL-6 in patients with gastric carcinoma." (PMID 40599771, 2025). "Targeted therapy against the IL-6 pathway has emerged as a promising approach for the prevention and treatment of PC metastasis from gastric cancer, based largely on pre-clinical studies." (PMID 38689325, 2024). "The impact of trastuzumab (10 μg/mL), LES-6400 (1 μM), doxorubicin (1 μM), and their combinations (trastuzumab with LES-6400 or doxorubicin) on the concentration of IL-6 in AGS human gastric cancer cells was examined." (PMID 39519758, 2024). "A recent investigation has revealed that the expression of five genes linked to the cGAS-STING pathway, namely IFNB1, IFNA4, IL6, NFKB2, and TRIM25, exhibits potential as a valuable prognostic marker for OS in patients suffering from gastric cancer." (PMID 38240703, 2024). "Experimental evidence indicates that IL-6 enhances the proliferation and invasiveness of stomach cancer cell lines, and the overexpression of IL-6 in mice results in the development of multiple carcinomas." (PMID 38422751, 2024). "Surprisingly, expression of YAP1, STAT3, IL11, or IL6 mRNA transcripts remained comparable across the molecular subtypes of gastric cancer." (PMID 37957015, 2024). "In gastric cancer, IL6 can exert its influence on invasion and progression via the activation of the JAK2/STAT3 pathway, which is the well-known signaling pathway induced by IL6." (PMID 39251966, 2024).
gastric cancer (continued). "The activation of the IL6/JAK2/STAT3 signaling cascade by SPI1 promotes gastric cancer malignancy and proliferation." (PMID 39309860, 2024). "PD‐L1 gene expression is regulated by the inflammatory cytokines TNF‐α and IL‐6 secreted by infiltrated macrophages in gastric cancer." (PMID 38660687, 2024). "The study highlights that FAK/YAP signaling promotes IL-6 expression in gastric cancer cells, and IL-6 acts as a positive feedback loop to activate the PI3K/AKT pathway further to produce more periostin." (PMID 38562556, 2024). "Several previous studies have demonstrated IL6 expression is upregulated in gastric cancer and affects its progression." (PMID 39251966, 2024). "In contrast, IL-6 can reverse this inhibition, indicating that this miRNA can inhibit the distant metastasis of gastric cancer by suppressing the IL-6-STAT3 pathway." (PMID 39309860, 2024). "The epithelial–mesenchymal transition (EMT) of gastric cancer cells is induced by CAF-secreted IL-6." (PMID 38398148, 2024). "IL-6 secreted by CAFs has been reported to promote epithelial-mesenchymal transition and metastasis of gastric cancer via the JAK2/STAT3 signaling pathway." (PMID 38510850, 2024). "An increase in MALAT1 expression in gastric cancer cells diminishes autophagy and quickens the secretion of IL-6, an activator of CAFs." (PMID 39717771, 2024). "Both IL-1 and IL-6 are involved in the growth of neoplastic cells in gastric cancer and the metastasis formation." (PMID 38398148, 2024). "Another inflammation-related signaling cascade inducing CDX2 in gastric cancer cells is the interleukin 6 (IL6) cascade, which activates JAK/STAT and ERK/MEK signaling." (PMID 39768557, 2024). "Research indicates that IL-6 boosts the proliferation and invasiveness of stomach cancer cell lines, while its overexpression in mice triggers the development of multiple carcinomas." (PMID 39816318, 2024). "Our research results indicate that LDN reduces the expression level of TLR4 in gastric cancer tissue and increases the expression level of IL-6 in gastric cancer tissue." (PMID 38720250, 2024). "An interesting strategy in gastric cancer is to investigate the efficacy and safety of napabucasin in combination with an anti-IL-6 antagonist." (PMID 39003350, 2024). "Ting Li and colleagues investigated cellular feedback mechanisms and reported an IL6-induced positive regulatory circuit in which miR-520d-5p modulates cyclophilin B (CypB) mRNA, influencing the growth of gastric cancer via changes in STAT3 phosphorylation." (PMID 39309860, 2024). "Qingqing Zhou and colleagues highlighted the role of VPS35 in increasing the growth and metastatic spread of gastric cancer cells through the IL-6/STAT3 signaling pathway." (PMID 39309860, 2024). "PPI analysis revealed five important proteins, such as ALB, BCL-2, NF-κB, HIF1A, and IL6, from 44 target proteins of gastric cancer according to statistical significance." (PMID 39816318, 2024). "Interleukin-6 (IL-6) and interleukin-8 (IL-8) are important pro-angiogenic factors in gastric cancer through the induction of vascular endothelial growth factor (VEGF)." (PMID 38398148, 2024). "Once activated, these CAFs secrete more IL-6, establishing a positive feedback loop that accelerates gastric cancer progression." (PMID 39717771, 2024). "Pre-operative serum IL-6 and CRP levels are associated with poor prognosis in patients with operable gastric cancer, suggesting potential prognostic utility as biomarkers." (PMID 38689325, 2024). "IL-6 level on POD 3 is an excellent predictor of infectious complications following laparoscopic gastric cancer surgery." (PMID 38504206, 2024).
gastric cancer (continued). "EGCG also exerts inhibitory effects on VEGF level and secretion triggered by IL-6, as well as gastric carcinoma cells’ angiogenesis by suppressing STAT3 activity." (PMID 38611849, 2024). "That is, LOC339059 plays an inhibitory role in influencing the malignant phenotype of gastric cancer, at least partially by down-regulating IL-6." (PMID 38001573, 2023). "The results confirmed that GRP78-overexpressing gastric cancer cells induced macrophage IL-6 expression and that the conditioned medium containing macrophages enriched the CD44+ gastric CSC population through the TGF-β1 signaling pathway." (PMID 36838713, 2023). "DC-10s is a subset of tolerogenic DCs which express high levels of HLA-G and secrete IL-10 and IL-6 in peripheral blood of patients with gastric cancer." (PMID 36053326, 2023). "The results revealed that GRP78 regulated the expression of TGF-β1 and TGF-β1-mediated stemness in human gastric cancer cells and that TGF-β1 derived from gastric cancer cells promoted macrophage polarization and IL-6 secretion." (PMID 36838713, 2023). "IL-6 can regulate M2-type macrophage polarization by activating the JAK2/STAT3 signaling in gastric cancer cells." (PMID 37679346, 2023). "The blockade of COX-2 production and TLR4 signaling attenuated the LPS- and HM-induced PGE2 and IL-6 secretion in the human gastric cancer epithelial cell line AGS." (PMID 37658354, 2023). "In this study, IL-6 levels were increased in macrophages treated with a conditioned medium containing GRP78-OE and decreased in GRP78-OE containing SB431542, indicating that gastric cancer induced macrophage IL-6 elevation through the GRP78-TGF-β1 pathway." (PMID 36838713, 2023). "We also investigated the molecular mechanism by which LOC339059, as a tumor suppressor, inhibits PDL1 and macrophage M2 polarization by modulating the activity of the IL-6/STAT3 axis in gastric cancer cells." (PMID 38001573, 2023). "Protein–protein interaction and co-expression analysis showed a strong association of CXCL1 with CXCR1, CXCR2, IL6, and IL1B in human gastric cancer tissue samples." (PMID 36614235, 2023). "In the cases of lung and gastric cancers, CAFs release IL‐6, which has been found to enhance the migration and invasion of cancer cells while also inducing the expression of genes linked to EMT and metastasis." (PMID 37605453, 2023). "Ham et al20 also confirm the link between IL-6’s impact on malignant-linked fibroblasts in the malignant stroma and the MDR of gastric cancer cells." (PMID 37062547, 2023). "It has also been reported that MSCs present in gastric cancer, by producing IL-6 through the STAT3-ERK1/2 signaling pathway, promote neutrophils and their shift towards the supportive phenotype of cancer cells." (PMID 38022534, 2023). "In a previous study by our group, we found elevated levels of interleukin 6 (IL-6) in gastric cancer patients which correlated negatively with the disease stage." (PMID 37447236, 2023). "The scientists discovered that IL-6 is a chromatin assembly factor-1 (CAF)-a specific secretory protein that confers chemoresistance to gastric cancer cells through paracrine signaling." (PMID 37062547, 2023). "In this study, we investigated the effects of herbal melanin (HM), extracted from the seed coats of the Nigella sativa (L.)plant, on COX-2, PGE2 and IL-6 production using the human gastric cancer cell line AGS." (PMID 37658354, 2023). "17β-estradiol has also been reported to inhibit the migration of gastric cancer cells by inhibiting CCL-5 and the IL-6-induced phosphorylation of Src, Cas, and paxillin in human gastric cancer cells." (PMID 37175948, 2023). "It is particularly notable that the increase in IL-6 was most substantial in East Asia and the Middle East, which are the specific regions with the highest rate of stomach cancer." (PMID 37006300, 2023). "Both NP sizes accumulated in gastric cancer cells; the effects on cellular viability were paradoxical; but they both upregulated IL-6 and IL-8." (PMID 37492595, 2023).
gastric cancer (continued). "T. erecta has been studied for its ability to regulate NF-κB and p65 signaling in gastric cancer, induce anti-inflammatory responses, and reduce IL-6 levels." (PMID 38139287, 2023). "In this study, macrophage-derived IL-6 was regulated by the GRP78-mediated secretion of TGF-β1 in gastric cancer cells." (PMID 36838713, 2023). "Gastric cancer cells secrete IL-6, and increased serum and tumor-tissue amounts of IL-6 possibly regulate tumor growth and development." (PMID 36430792, 2022). "The data also suggests novel therapeutic directions such as blocking IL-6 signaling from myeloid cells and plasminogen activation in activated endothelial cells for treating gastric cancer." (PMID 36550535, 2022). "The expression/activation of IL-6, p-Stat3, PD-1 and PD-L1 in gastric cancer (GC) tissues were examined to evaluate their abilities in predicting the survival prognosis in postoperative patients with GC." (PMID 36454780, 2022). "Univariate analysis for the association of various clinicopathologica features with SAA and IL-6 expressions of patients with gastric cancer." (PMID 36316846, 2022). "The antiproliferative effect of piperine against gastric cancer cells (TMK-1) was found to be due to inhibition of IL-6, along with the inhibition of STAT3 and p38 MAPK pathways." (PMID 36428575, 2022). "Inflammatory cytokines that support gastric cancer-related inflammation include IL-1, IL-6, IL-18, TNF-α, and TGF-β." (PMID 35892729, 2022). "Paeoniflorin is reported to interfere with the pro-metastasis functions of CAFs in gastric cancer stroma by the inhibition of IL-6 and micro-RNA-149." (PMID 35327514, 2022). "M2 macrophages recruited to the tumor microenvironment can also release IL-6, which promotes programmed cell death-ligand 1 (PD-L1) expression and proliferation of gastric cancer cells." (PMID 36233285, 2022). "In gastric cancer, the increase of MPV was associated with chronic inflammation and elevated IL-6 concentration, which causes the maturation and proliferation of megakaryocyte and the enhanced release of platelets." (PMID 36185270, 2022). "Previous studies have revealed the antitumor mechanism of KAI that inhibits gastric cancer cell proliferation through the interleukin-6/STAT3 pathway." (PMID 36093402, 2022). "Several studies have demonstrated that IL-6-, IL-8-, IL-10-, and IL-33 mediated pathways are involved in the invasion and metastasis of gastric cancer." (PMID 35368661, 2022). "It has been shown that circRBM33 silencing inhibits proliferation, migration, and invasion, and promotes apoptosis of gastric cancer cells through targeting the miR-149/IL-6 axis." (PMID 35318311, 2022). "It is known that IL6 is responsible for gastric cancer induction and leads to cancer cell invasion by activating the c-Src/RhoA/ROCK axis." (PMID 36428575, 2022). "Spearman’s correlation analysis for the association of clinicopathologica features with serum SAA and IL-6 expressions of patients with gastric cancer." (PMID 36316846, 2022). "Increased expression of tumor-related inflammatory mediators and cytokines, such as tumor necrosis factor-α, interleukin-1 (IL-1), and IL-6, have been reported to be increased in gastric cancer cases and other cancers." (PMID 36387250, 2022). "It was identified that IL-6 is overexpressed in the stromal portion of gastric cancer and the elevated IL-6 stimulates the Jak1-STAT3 pathway in gastric cancer via paracrine signaling." (PMID 36140220, 2022). "In conclusion, textural features of perigastric AT on [18F]FDG PET/CT were significantly associated with macrophage infiltration and IL-6 expression in perigastric AT; additionally, these were significant predictors of RFS in patients with gastric cancer." (PMID 36233285, 2022). "In our previous study, we showed the anti-metastatic activity of piperine via the modulation of interleukin-6 expression by multiple molecular mechanisms in gastric cancer cells." (PMID 35326180, 2022).
gastric cancer (continued). "In gastric cancer, IL-6 induces the differentiation of M2 macrophages and promotes the secretion of tumor-promoting cytokines, such as IL-10 and TGF-β, by M2 macrophages, thus facilitating tumor growth and tumor metastasis." (PMID 35701829, 2022). "Hyper-activation of the IL6-JAK-STAT3 signaling pathway is related with poor prognosis survival of stomach cancer patients." (PMID 35712475, 2022). "More recent studies using gene expression analysis of patients with prechemotherapy treated gastric cancer identified an IL6 stromal signature predictive of poor response to chemotherapy." (PMID 35313341, 2022). "Gastric cancer derived mesenchymal cells secrete IL-6 and IL-8 (CXCL8) through JAK2/STAT3 signaling pathway and induce polarization of gastric cancer M2-macrophages." (PMID 35479325, 2022). "IL-6/Stat3 signaling pathway promotes the proliferation, invasion and lymphangiogenesis of gastric cancer cells by stimulating JAK-STAT3-VEGF-C signaling pathway." (PMID 36454780, 2022). "This study provided evidence for crosstalk between gastric cancer cells and CAFs by IL-6, which is a key contributor to chemoresistance." (PMID 35740372, 2022). "Reports show that RBM33 promotes the progression of gastric cancer by targeting miR-149 to regulate IL-6, and that the circular RNA of RBM33 is involved in the progression of cervical cancer by regulating the miR-758-3p/PUM2 axis." (PMID 35368875, 2022). "This is generated by a mechanism dependent on gastric cancer-derived mesenchymal stromal cells, which can secrete IL-6 and IL-8 to polarize TAMs toward the M2 phenotype, so that the polarized TAM-M2 can favor the EMT metastatic process in GC cells." (PMID 34503571, 2021). "Recent studies demonstrated that CAFs induce inhibitory immune cell infiltration and chemotherapy resistance in gastric cancer by activating the NF-κB signaling pathway to secrete IL6, IL8, and other inflammatory factors." (PMID 33731686, 2021). "The IL-6/STAT3 signaling pathway has been investigated in gastric cancer research, and activation of IL6ST enhances carcinogenesis." (PMID 33995063, 2021). "It has been suggested that CAFs secrete IL6 promotes the metastasis and a key contributor to chemoresistance of gastric cancer cells." (PMID 35008304, 2021). "Piperine was found to inhibit IL-6 expression, further suppressing cell invasion of gastric cancer cells (TMK-1)." (PMID 35069196, 2021). "Conversely, SK1 was dispensable for IL-6 and IL-8 expression induced by lysophosphatidic acid in gastric cancer cells." (PMID 33414460, 2021). "In our present study, we demonstrated that ZIPK activates IL‐6/STAT3 signaling pathway via Ser727 phosphorylation in gastric cancer cells." (PMID 34375503, 2021). "In this context, IL-6 behaves as a pro-metastatic agent as described in the human gastric cancer AGS and MKN-28 cell lines." (PMID 34885656, 2021). "Stattic strongly reduced STAT3 phosphorylation and the mRNA levels of IL‐6 in gastric cancer cells with high ZIPK expression." (PMID 34375503, 2021). "In gastric cancer, serum-derived IL-6 activates and induces MDSCs, which express arginase 1, via the PI3K-Akt signaling pathway, thereby suppressing cytotoxic T cell functionality." (PMID 33981768, 2021). "It was found that gastric cancer-derived isolated CAFs produced high amounts of IL-6 that enhance migration and EndMT of gastric cancer cells, a phenotype that was abrogated by inhibition of IL-6." (PMID 33806468, 2021). "ZIPK activates the IL‐6/STAT3 signaling pathway via Ser727 phosphorylation in gastric cancer cells and increases IL‐6‐induced STAT3‐dependent transcription." (PMID 34375503, 2021). "Based on the results that GC-EVs were associated with skewing macrophages, and the resultant macrophages further secreted IL-6 and affected the phenotypes of cancer cells, GC-EVs must be playing a role in aggravating gastric cancer malignancy." (PMID 33509150, 2021).